LRRC72 (leucine rich repeat containing 72)
Synonyms: CFAP279; FAP279
Tractability: No criterion of Open Targets' tractability assessment is met for any kind of drug.
Gene: Protein-coding gene on chromosome 7 (16,526,825 to 16,581,568, forward strand). Ensembl gene ENSG00000205858.
Genetic constraint (gnomAD): Loss-of-function variants: 16 observed, 12.85 expected, observed/expected ratio (o/e) 1.25, 90% interval 0.84 to 1.8. The upper end of that interval is the gene's LOEUF score, 1.8, which puts it in group 6 of 6, group 1 being the genes least tolerant of losing a copy. Missense variants: 225 observed, 170.92 expected, observed/expected ratio (o/e) 1.32, 90% interval 1.18 to 1.47. Synonymous variants: 65 observed, 62.87 expected, observed/expected ratio (o/e) 1.03, 90% interval 0.85 to 1.27.
Homologues: Orthologues: chimpanzee LRRC72 (99% identical), macaque LRRC72 (95% identical), pig LRRC72 (87% identical), dog LRRC72 (82% identical), rabbit LRRC72 (79% identical). Paralogues in human: LRMDA (20% identical), SNRPA1 (18% identical).
Diseases named in the same sentence as LRRC72 in open-access papers:
LRRC72 is named in the same sentence as 3 diseases in open-access papers, as found by Europe PMC text mining. Sharing a sentence is not in itself a finding about the gene and the disease. The quoted sentences say what the papers report.
astrocytoma (2 papers, 2023 to 2024). "Interestingly, there were two CpGs with decreased 5-hmC levels and increased gene expression in astrocytoma, ependymoma, and glioneuronal/neuronal tumors: cg18280362 located in the promoter region of CWH43 and cg08278401 located in the promoter region of LRRC72." (PMID 36909536, 2023).
LRRC72 also shares sentences with these, for which no sentence is quoted: ependymoma (2 papers); neuronal tumor (2).